AKIRIN2 (akirin 2)
Description:
Molecular adapter that acts as a bridge between a variety of multiprotein complexes, and which is involved in embryonic development, immunity, myogenesis and brain development. Plays a key role in nuclear protein degradation by promoting import of proteasomes into the nucleus: directly binds to fully assembled 20S proteasomes at one end and to nuclear import receptor IPO9 at the other end, bridging them together and mediating the import of pre-assembled proteasome complexes through the nuclear pore. Involved in innate immunity by regulating the production of interleukin-6 (IL6) downstream of Toll-like receptor (TLR): acts by bridging the NF-kappa-B inhibitor NFKBIZ and the SWI/SNF complex, leading to promote induction of IL6 (By similarity). Also involved in adaptive immunity by promoting B-cell activation (By similarity). Involved in brain development: required for the survival and proliferation of cerebral cortical progenitor cells (By similarity). Involved in myogenesis: required for skeletal muscle formation and skeletal development, possibly by regulating expression of muscle differentiation factors (By similarity). Also plays a role in facilitating interdigital tissue regression during limb development (By similarity).
Synonyms: C6orf166; FLJ10342; dJ486L4.2; FBI1
Tractability: PROTAC: UniProt records ubiquitination sites on it; ubiquitination databases record sites on it.
Gene: Protein-coding gene on chromosome 6 (87,674,860 to 87,702,255, reverse strand). Ensembl gene ENSG00000135334.
Subcellular location: Nucleus; Cytoplasm; Membrane
Subcellular location (Human Protein Atlas): Nucleoplasm
Gene Ontology:
Molecular function: enzyme binding; identical protein binding; protein binding; protein-macromolecule adaptor activity; transcription coregulator activity
Biological process: nuclear protein quality control by the ubiquitin-proteasome system; proteasome localization; protein import into nucleus; cerebral cortex development; defense response to bacterium; positive regulation of adaptive immune response; positive regulation of innate immune response; positive regulation of interleukin-6 production; positive regulation of transcription by RNA polymerase II; embryo development ending in birth or egg hatching; positive regulation of B cell activation; regulation of muscle cell differentiation
Cellular component: nucleoplasm; nucleus; chromatin; cytoplasm; membrane; transcription repressor complex
Genetic constraint (gnomAD): Loss-of-function variants: 6 observed, 25.78 expected, observed/expected ratio (o/e) 0.23, 90% interval 0.13 to 0.46. The upper end of that interval is the gene's LOEUF score, 0.46, which puts it in group 2 of 6, group 1 being the genes least tolerant of losing a copy. Missense variants: 210 observed, 240.59 expected, observed/expected ratio (o/e) 0.87, 90% interval 0.78 to 0.98. Synonymous variants: 128 observed, 102.72 expected, observed/expected ratio (o/e) 1.25, 90% interval 1.08 to 1.44.
Homologues: Orthologues: chimpanzee AKIRIN2 (100% identical), dog AKIRIN2 (98% identical), pig AKIRIN2 (98% identical), rabbit AKIRIN2 (97% identical), mouse Akirin2 (94% identical), rat Akirin2 (93% identical), macaque AKIRIN2 (84% identical), tropical clawed frog akirin2 (76% identical), zebrafish akirin2 (74% identical), guinea pig AKIRIN2 (66% identical), Drosophila melanogaster akirin (39% identical), Caenorhabditis elegans akir-1 (30% identical). Paralogues in human: AKIRIN1 (56% identical).